PIN1 (peptidylprolyl cis/trans isomerase, NIMA-interacting 1)
Diseases named in the same sentence as PIN1 in open-access papers (continued):
Sharing a sentence is not in itself a finding about the gene and the disease.
gastric cancer (continued). "To reveal PIN1-targeted miR in gastric cancer, we predicted the potential miRs at five databases, including miRTarBase, TargetScan, miRNApath, starBase, and miRanda." (PMID 32703934, 2020). "In this work, we demonstrated that PIN1 also facilitates the migration and invasion of gastric cancer." (PMID 32703934, 2020). "Recently, researches indicated that PIN1 also high expressed in gastric cancer that promotes its proliferation and chemoresistance." (PMID 32703934, 2020). "Research above has indicated that miR-628-5p suppresses the expression of PIN1 and progression of gastric cancer." (PMID 32703934, 2020). "In summary, our research indicated that miR-628-5p is a novel miR that suppress gastric cancer by targeting PIN1 directly." (PMID 32703934, 2020). "In this study, we revealed that PIN1 not only increases the proliferation and colony formation of gastric cancer, but also promotes its invasion and migration." (PMID 32703934, 2020). "Researches have revealed that miR-200b-3p13, miR-200c-3p14, miR-296-5p15, miR-874-3p16, miR-370-3p17, and miR-140-5p18 inhibit PIN1 in different cancers but gastric cancer." (PMID 32703934, 2020). "In human gastric cancer cells PIN1 induces a conformational change of phosphorylated BRD4 supporting its interaction with CDK9, thus improving BRD4-mediated gene expression relevant for gastric cancer cell proliferation and tumor development." (PMID 30873382, 2019). "It was confirmed that PIN1P1 could promote gastric cancer cell proliferation, migration and invasion, which is consistent with the oncogenic effects of PIN1 in gastric cancer." (PMID 37929660, 2024). "PIN1 facilitated gastric cancer cell proliferation, migration and invasion." (PMID 37929660, 2024). "As we have shown that PIN1P1 could promote PIN1 expression, we next explored the expression of PIN1 in gastric cancer tissues and its function in gastric cancer cells." (PMID 37929660, 2024). "PIN1 is upregulated in gastric cancers and is a valuable target in these tumours." (PMID 37929660, 2024). "PIN1P1 was identified to directly bind to the YBX1 protein, which may mediate PIN1 upregulation and promote gastric cancer progression." (PMID 37929660, 2024). "In gastric cancer, miR-628-5p targets PIN1 to inhibit cancer progression." (PMID 35113786, 2022). "Additionally, we detected the expression of PIN1 by IHC in a tissue chip containing 66 pairs of gastric cancer and adjacent tissues." (PMID 32703934, 2020). "In this work, we firstly demonstrated that miR-628-5p inhibits gastric cancer by targeting PIN1." (PMID 32703934, 2020). "Researches have indicated that PIN1 is upregulated in multiple cancers including gastric cancer." (PMID 32703934, 2020). "Inhibiting PIN1 by shRNA suppresses the progression of gastric cancer significantly." (PMID 32703934, 2020). "Besides, we demonstrated that miR-628-5p is a novel PIN1-targeted microRNA, and the expression of miR-628-5p is negatively correlated with PIN1 in gastric cancer." (PMID 32703934, 2020). "Our following research aimed to determine whether miR-628-5p suppresses gastric cancer through inhibiting PIN1." (PMID 32703934, 2020). "Pin1 is overexpressed and correlated with poor prognosis in gastric cancer." (PMID 32258027, 2020). "However, the mechanism of PIN1 high expression and its function in gastric cancer progression are still unclear." (PMID 32703934, 2020). "To identify novel PIN1-targeted miR, we then detected whether the thirty unreported miRs suppress PIN1 expression in gastric cancer." (PMID 32703934, 2020). "Accordingly, we project to detected the function of PIN1 on gastric cancer metastasis." (PMID 32703934, 2020). "However, as in other cancers, the expression of miR-628-5p is deficient in majority of gastric cancer tissues especially in metastasis tissues that contributes to the high expression of PIN1 and facilitates the progresses of gastric cancer." (PMID 32703934, 2020).
gastric cancer (continued). "However, the mechanism of PIN1 high expression in gastric cancer is still unclear." (PMID 32703934, 2020). "Interestingly, we found that PIN1 also inhibits the cytoplasm location of XPO5 in gastric cancer but it has tiny influence on the miR-628-5p expression, indicating that other exportin protein may involved in pre-miR transport." (PMID 32703934, 2020). "PIN1, the parental gene of PIN1P1, was elevated in gastric cancer tissues, and its upregulation was correlated with poor patient outcomes." (PMID 37929660, 2024). "We reveal that the pseudogene PIN1P1 promotes the progression of gastric cancer by interacting with YBX1 and activating PIN1." (PMID 37929660, 2024). "PIN1 also catalyzes the isomerization of BRD4 Pro205 and induces its conformation change to promote CDK9 interaction and transcriptional activity and gastric cancer cell proliferation." (PMID 34540900, 2021). "Prolyl isomerase PIN1 regulates the stability and transcriptional activity and oncogenic potential of BRD4 in gastric cancer cells." (PMID 34540900, 2021). "The result demonstrated that PIN1 significantly promotes the expression of cyclin D1, MMP2, MMP9, β-catenin, and N-cadherin, while inhibits E-cadherin expression in gastric cancer." (PMID 32703934, 2020). "Result revealed that PIN1 is upregulated in most gastric cancer cell lines comparing with GES and it’s high expressed in 70.83% (17/24) of gastric cancer patients." (PMID 32703934, 2020). "Here we found that in gastric cancer, PIN1P1 interacted with YBX1, upregulating its protein expression, which in turn enhanced the expression of PIN1, in which transcription factor E2F1 may be involved." (PMID 37929660, 2024). "Importantly, recent study also showed that Pin1 inhibition by ATRA or short hairpin RNA, reduces cancer development by inhibiting Wnt/β-catenin and PI3K/AKT signaling pathways in gastric cancer." (PMID 34805153, 2021). "Moreover, Pin1 enhances the stability of BRD4 by inhibiting its ubiquitination and increasing transcriptional activity of BRD4 to promote the proliferation of gastric cancer." (PMID 32296699, 2020). "PIN1 stabilizes BRD4 protein to increase the migration and proliferation of gastric cancer." (PMID 32258027, 2020). "Pin1 inhibition using small molecule inhibitor such as ATRA or short hairpin RNA, reduces cancer development by inhibiting Wnt/β-catenin and PI3K/AKT signaling pathways in gastric cancer." (PMID 32258027, 2020).
melanoma (14 papers, 2013 to 2025). A malignant, usually aggressive tumor composed of atypical, neoplastic melanocytes. "In primary melanoma, only cytoplasmic Pin1 expression was associated with worse 5-year melanoma-specific survival (P = 0.035, log-rank test)." (PMID 30442923, 2018). "In contrast, nuclear Pin1 expression was only associated with melanoma-specific 5-year survival (P = 0.030, log-rank test)." (PMID 30442923, 2018). "Kaplan-Meier survival analysis showed that increased cytoplasmic Pin1 expression was associated with a worse 5-year melanoma-specific survival of melanoma (P < 0.001) and metastatic melanoma patients (P = 0.004)." (PMID 30442923, 2018). "Compared with neonatal human epidermal melanocytes, BRAFV600E-mutated Colo829 human melanoma cells showed enhanced expression of Pin1, FOXM1, CENPF and Cyclin B1 both at the mRNA and protein levels." (PMID 26279295, 2016). "Similarly, in metastatic melanoma, cytoplasmic Pin1 expression was associated with both overall and melanoma-specific 5-year survival (P = 0.004 and 0.050, respectively, log-rank test)." (PMID 30442923, 2018). "A later study demonstrated that high level of Pin1 expression could maintain Notch signalling, which is an important pathogenesis mechanism in melanoma, and is associated with worse prognosis." (PMID 30442923, 2018). "However, the regulatory mechanisms underlying this significant increase of cytoplasmic Pin1 expression in melanoma are largely unknown." (PMID 30442923, 2018). "Pin1 is overexpressed in several cancers, including breast, prostate, lung, ovarian, and cervical carcinomas, as well as melanoma and glioma." (PMID 37050909, 2023). "SUV39H1/DNMT3A-dependent methylation of the RB1 promoter stimulates PIN1 expression and melanoma development." (PMID 33234142, 2020). "Very recently, Pin1 was reported to stimulate FoxM1 activity in metastatic melanomas and chemo-resistant cervical cell lines." (PMID 30321399, 2019). "Pin1 is overexpressed and activated in different kinds of cancer including breast, lung, gastric, melanoma, prostrate, ovary and cervical cancers and its overexpression correlates with poor clinical outcome in human cancer patient." (PMID 31015482, 2019). "Our findings provide strong evidence that cytoplasmic Pin1 expression is a prognostic marker and a promising therapeutic target in melanoma." (PMID 30442923, 2018). "In samples from all 538 melanoma patients, we investigated the correlation between cytoplasmic and nuclear Pin1 expression and clinicopathologic parameters." (PMID 30442923, 2018). "All melanoma cell lines (8/8) showed increased Pin1 protein levels compared with normal melanocytes." (PMID 30442923, 2018). "Our data demonstrated that cytoplasmic Pin1 expression was negatively correlated with melanoma patient 5-year survival in the discovery set TMA (114 cases), a finding that was confirmed in the validation set TMA (404 cases)." (PMID 30442923, 2018). "Our data demonstrated that cytoplasmic Pin1 expression significantly increases with melanoma progression, and nuclear Pin1 expression shows a decrease in metastatic melanoma compared to early stage skin lesions." (PMID 30442923, 2018). "Multivariate Cox regression analysis showed that cytoplasmic Pin1 expression is an independent prognostic factor in melanoma." (PMID 30442923, 2018). "High expression (IRS 0–8) of cytoplasmic Pin1 was observed in 3.13%, 8.33%, 16.49% and 22.76% of the biopsies in normal nevi, dysplastic nevi, primary melanoma and metastatic melanoma, respectively." (PMID 30442923, 2018). "In the present study, aiming at an improved understanding of the role of Pin1 in melanoma progression, we used large-scale TMAs and immunohistochemistry to investigate Pin1 expression in 655 cases of pigmented skin lesions." (PMID 30442923, 2018). "Our data indicate that cytoplasmic Pin1 plays an important role in melanoma pathogenesis and progression, and serve as a potential prognostic marker for melanoma." (PMID 30442923, 2018).
melanoma (continued). "The authors investigated the expression level of Pin1 and analyzed the prognostic value of Pin1 expression using a large-scale melanoma tissue microarray study." (PMID 30442923, 2018). "Pin1 mRNA as determined by RT-PCR was increased 7.3 folds on average in all melanoma cell linesas compared with normal melanocytes with 4/8 cell lines showing a >10-fold increase." (PMID 30442923, 2018). "The exact mechanism of regulation of Pin1 expression and cellular localization in melanoma as well as their functional consequences remains to be established." (PMID 30442923, 2018). "Nuclear Pin1 expression decreased from thin melanoma (thinner than 2 mm) to thick melanoma (greater than 2 mm) (P = 0.001, χ2 test)." (PMID 30442923, 2018). "Our data showed that cytoplasmic Pin1 is an independent factor for predicting both overall and melanoma-specific patient survival (P = 0.001 and 0.000, respectively)." (PMID 30442923, 2018). "Statistical analysis revealed that the differences between high and low Pin1 expression cohorts are significant (overall survival, P < 0.001; melanoma-specific survival, P < 0.001)." (PMID 30442923, 2018). "To investigate the role of Pin1 in melanoma progression, we checked Pin1 expression in different stages of melanocytic lesions using tissue microarray (TMA) and immunohistochemistry." (PMID 30442923, 2018). "High expression of cytoplasmic Pin1 was correlated with worse patient 5-year overall survival and melanoma-specific survival (P = 0.015 and 0.010, χ2 test)." (PMID 30442923, 2018). "We first investigated the expression level of Pin1 in melanoma cell lines and normal melanocytes by Western blot." (PMID 30442923, 2018). "To further investigate the expression profiles of Pin1 in melanoma tissue, we conducted immunohistochemistry staining on both discovery set and validation set melanoma TMAs." (PMID 30442923, 2018). "These approaches yielded around one hundred possible PIN1 covalent binders that were tested afterwards for cytotoxicity against melanoma A375 cells using the MTT viability assay." (PMID 28598431, 2017). "Subsequently, we determined to what extent these results hold true in humans, by using a patient-derived skin and melanoma sample in which we were able to perform direct co-staining using a mouse-Pin1 antibody." (PMID 26279295, 2016). "Although the nevus again only revealed background levels of Pin1 expression, Pin1 was elevated in the adjacent melanoma." (PMID 26279295, 2016). "With the blockage of PIN1 by stable transfection of a microRNA (miRNA) plasmid targeting PIN1, the proliferation and invasion of cells from the malignant melanoma A275 cell line were significantly reduced." (PMID 24179535, 2013). "Despite most studies suggesting Pin1 is pro-cancerous, it has also been observed that Pin1’s high expression correlates with a better prognosis in melanoma, prostate, and testis cancer patients, as revealed from a bioinformatics analysis of tumors in the Human Protein Atlas." (PMID 37508437, 2023). "While normal tissues and cell lines only express low levels of Pin1, which fluctuate during the cell cycle, Pin1 is overexpressed and/or activated in various human cancers, including breast, ovary, prostate, lung, gastric, and cervical cancers, as well as melanoma." (PMID 37050909, 2023). "Moreover, cytoplasmic Pin1 expression is also an independent factor for primary melanoma patient 5-year melanoma-specific survival (P = 0.039)." (PMID 30442923, 2018). "Furthermore, cytoplasmic Pin1 expression is significantly correlated with 5-year survival in metastatic as well as in all melanoma patient cohorts, and cytoplasmic Pin1 is an independent prognostic factor for melanoma patient survival." (PMID 30442923, 2018).
melanoma (continued). "Significant differences for cytoplasmic Pin1 staining were observed between normal nevi and metastatic melanoma (P = 0.011, χ2 test), between dysplastic nevi and primary melanoma (P = 0.046, χ2 test) and between dysplastic nevi and metastatic melanoma (P = 0.016, χ2 test)." (PMID 30442923, 2018). "Based on the widely accepted oncogenic role of Pin1 in cancer, we hypothesized that Pin1 would have profound impact on melanoma pathogenesis and progression." (PMID 30442923, 2018). "Due to loss of biopsy cores or insufficient tumor cells present in the cores, 656 biopsies (32 normal nevi, 86 dysplastic nevi, 347 primary melanomas, and 191 metastatic melanomas) could be evaluated for Pin1 staining." (PMID 30442923, 2018). "To date, very few publications focused on the role of Pin1 in melanoma." (PMID 30442923, 2018). "Our results suggest that elevated Pin1 activity might be required for melanoma transformation and progression." (PMID 30442923, 2018). "Moreover, Multivariate Cox proportional regression analysis indicated that high cytoplasmic Pin1 expression was an independent prognostic factor for melanoma." (PMID 30442923, 2018). "Finally, we conducted Multivariate Cox regression analysis to investigate the correlation between cytoplasmic Pin1 expression and melanoma patient survival." (PMID 30442923, 2018). "Importantly, CENPF expression was elevated in the same area, indicating that in the Pin1-positive melanoma FOXM1 signaling is active." (PMID 26279295, 2016). "The Pin1-FOXM1 interaction was enhanced by BRAFV600E, the driver oncogene in the majority of melanomas, and in extrapolation of the correlation data, interference with\ Pin1 in BRAFV600E-driven metastatic melanoma cells impaired both FOXM1 activity and cell survival." (PMID 26279295, 2016). "Altogether, these experiments indicate that (I) Pin1 correlates with FOXM1 expression and activity in malignant melanoma, (II) Pin is causally linked to FOXM1 activity through physical binding on MEK/ERK target sites and (III) oncogenic BRAF stimulates the Pin1-FOXM1 interaction through MEK." (PMID 26279295, 2016). "To determine whether the increased mRNA levels result in increased protein expression, we stained samples from a BRAFV600E-inducible mouse model that spontaneously develops melanomas, for Pin1 and FOXM1." (PMID 26279295, 2016). "However, nuclear Pin1 staining was increased when comparing normal nevi to dysplastic nevi (P = 0.193, χ2 test) but decreased in a comparison of dysplastic nevi with primary melanoma (P = 0.031, χ2 test)." (PMID 30442923, 2018). "Similar to the human and mouse melanoma samples and the MEF samples, Pin1 and CENPF co-expressed in individual Colo829 cells." (PMID 26279295, 2016). "Whereas the BRAFV600E-induced nevus showed only background staining for Pin1 and FoxM1, both were strongly elevated in a BRAFV600E-derived melanoma." (PMID 26279295, 2016). "However, similar to the discovery set, nuclear Pin1 expression was correlated neither with overall 5-year survival, nor with melanoma-specific 5-year survival (P = 0.636 and 0.719, respectively, log-rank test)." (PMID 30442923, 2018). "However, cytoplasmic Pin1 expression was not correlated with primary melanoma clinical outcome." (PMID 30442923, 2018). "Individual melanomas from independent data sets showed that FOXM1, CENPF and Cyclin B1, but not actin (control), significantly correlated with Pin1 expression." (PMID 26279295, 2016).